FMOD (fibromodulin)
Diseases named in the same sentence as FMOD in open-access papers (continued):
Sharing a sentence is not in itself a finding about the gene and the disease.
chronic lymphocytic leukemia (5 papers, 2013 to 2024). "Mayr and colleagues have reported that FMOD is a tumor-associated antigen in chronic lymphocytic leukemia via facilitating the expansion of specific CD8+ autologous T lymphocytes." (PMID 37965134, 2023). "Fibromodulin (encoded by FMOD) is thought to be involved in the inhibition of tumorigenesis and apoptosis in hematologic malignancies such as B-cell chronic lymphocytic leukemia and mantle cell lymphoma, like other proteoglycans." (PMID 33869043, 2021). "FMOD transcript over expression was described in B-cell chronic lymphocytic leukemia (CLL-B), and it has been suggested as a target for therapeutic approaches in this cancer." (PMID 31198406, 2019). "We have previously reported the unique expression of another SLRP, fibromodulin (FMOD) in the leukemic cells of patients with chronic lymphocytic leukemia (CLL)." (PMID 24499526, 2013). "For instance, analysis of differentially expressed and methylated genes shows the alterations of expression patterns and DNA methylation patterns of ADAMTS17, FMOD, and ZAP70 in chronic lymphocytic leukemia (CLL)." (PMID 38510251, 2024). "Correspondingly, targeting cell surface protein FMOD has been found to be a promising therapeutic approach for triple-negative breast cancer, colorectal cancer melanoma, and chronic lymphocytic leukemia." (PMID 37965134, 2023).
diabetes (5 papers, 2021 to 2025). "Research on FMOD and diabetes indicates that FMOD can downregulate genes related to diabetes, counteracting the effects of aging." (PMID 40309438, 2025). "On the other hand, it suggests FMOD inhibits aging by downregulating genes involved in muscle aging, diabetes, and intracellular lipid accumulation or by indirectly inhibiting their expressions by suppressing the activity of MSTN protein." (PMID 34440852, 2021). "Moreover, FMOD was detected in carotid atherosclerotic plaques from symptomatic and asymptomatic patients, while FMOD expression was significantly higher in plaques obtained from patients with diabetes and in those with an increased incidence of postoperative neurological events." (PMID 37483637, 2023). "Muscle aging (Atrogin 1 and Glb1), diabetes (RAGE and CD163), and intracellular lipid accumulation (CD36 and PPARγ) related mRNA and protein expressions and FMOD were analyzed in MSTN knockout gas muscles." (PMID 34440852, 2021). "Muscle aging is associated with diabetes and obesity, and in the present study, we compared the expressions of the FMOD and MSTN genes and those of genes related to muscle aging (Atrogin 1, Glb1), diabetes (RAGE, CD163) and intracellular lipid accumulation (CD36, PPARγ) in vivo and in vitro." (PMID 34440852, 2021). "Here, we report that FMOD and MYOG expressions were higher in the muscles of 16-week-old than in those of 2-year-old mice; however, expressions of muscle aging, diabetes, and intracellular lipid accumulation-related genes were higher in aged mice (2-year-old) muscles." (PMID 34440852, 2021). "Interestingly, FMOD gene expression was diminished in aged and HFD mouse muscles and in C2C12 cells cultured in the presence of ceramide or under adipogenic conditions during differentiation, whereas the expressions of genes related to aging, diabetes, and obesity and that of MSTN were all elevated." (PMID 34440852, 2021).
myopia (5 papers, 2008 to 2025). "Genetic studies of gene polymorphisms in humans also support a role for lumican in scleral involvement of myopia which is closely associated with fibromodulin." (PMID 35571611, 2022). "Another mouse study also implicated the proteoglycans-lumican and fibromodulin as functional candidate genes for high myopia." (PMID 20339468, 2009). "The Lumican-Fibromodulin double knockout mice displayed features of pathological myopia, including scleral thinning and retinal detachment." (PMID 40909333, 2025). "Apart from EGR1, myopia-like changes has been observed in lumican-fibromodulin double null mice." (PMID 18636116, 2008). "Similarly, no mutation in the lumican and fibromodulin genes has been identified in families with high myopia, although a report claimed an association of myopia with SNPs of lumican." (PMID 18636116, 2008).
breast carcinoma (4 papers, 2019 to 2024). "Previous reports have indicated that FMOD was regulated by the Wnt/β-catenin pathway in human breast cancer cell lines, MAPK/AP-1 pathway in human pancreatic stellate cells, and TGF-β2 in rat pericytes." (PMID 38706856, 2024). "Our previous study showed that β-catenin translocated into the nucleus to form a transcription complex with TCF4 and LEF1, which then promotes FMOD transcription, subsequently leading to breast cancer cell migration and invasion." (PMID 36986805, 2023). "Aspirin inhibits breast cancer metastasis by suppressing FMOD expression via the Wnt/β-catenin pathway." (PMID 36986805, 2023). "Our previous study indicated that aspirin inhibited breast cancer metastasis by attenuating the Wnt/β-catenin pathway and suppressing FMOD expression by inhibiting the HDAC6 deacetylation of β-catenin." (PMID 36986805, 2023). "Our results confirm and extend the involvement of Wnt/β-catenin pathway in various tumors by demonstrating the crucial role of the Wnt/β-catenin pathway in promoting breast cancer metastasis via regulating FMOD transcription." (PMID 31824307, 2019). "In one of our other studies (unpublished), FMOD was knocked out using the CRISPR/Cas9 system and it was observed that high expression of FMOD promoted breast cancer development and progression." (PMID 31824307, 2019). "In the present study, we demonstrate that in human and murine metastatic breast cancer cell lines, FMOD plays an essential role to promote BCCMI via activating ERK." (PMID 31824307, 2019). "We find for the first time that in breast cancer cells FMOD expression is regulated positively by the Wnt/β-catenin signaling pathway, and FMOD is transcribed by the β-catenin/TCF4/LEF1 transcription complex which binds to the FMOD promoter at specific sites." (PMID 31824307, 2019). "Our present study shows for the first time that FMOD is essential for breast cancer cell migration and invasion, which indicates that FMOD is likely a pro-metastatic factor in various cancers." (PMID 31824307, 2019). "In addition, FMOD is critical for breast cancer cell migration and invasion and is positively regulated by the β-catenin/TCF4/LEF1 complex." (PMID 36986805, 2023). "A short study using overexpression of FMOD in murine mammary carcinoma cell line 4T1 suggested that FMOD overexpression down regulates NF-κB and TGF-β1, implying that FMOD may inhibit cell migration which depends on the NF-κB and TGF-β1 signaling pathways." (PMID 31824307, 2019). "Meanwhile, we find that FMOD plays an essential role in breast cancer cell migration and invasion (BCCMI) via promoting ERK activation, and thus FMOD, as a transcriptional target gene of the Wnt/β-catenin pathway, mediates the promotive effects of the pathway on BCCMI." (PMID 31824307, 2019). "Thus our present study identifies the molecular and cellular mechanisms by which FMOD expression and BCCMI are regulated, and through which Aspirin exerts anti-metastatic effects on breast cancer by downregulating the HDAC6-β-catenin-FMOD-ERK axis." (PMID 31824307, 2019). "Therefore, in this study, we compared the expression of FMOD in wild type breast cancer cells with breast cancer cells that had undergone lentiviral FMOD knockdown although it should be noted that a limitation of our study is the lack of scramble shRNA to act as a negative control." (PMID 31824307, 2019). "Likewise, LiCl enhanced breast cancer cell motility; but the enhancement could be eliminated by knocking down FMOD, or individual components of the β-cat/TCF4/LEF1 transcriptional complex, or by inhibiting HDAC6 with Trichostatin A (TSA)." (PMID 31824307, 2019). "The role of fibromodulin and decorin for radiotherapy response in HNSCC is still unknown, but in a breast cancer cell line, 4T1, overexpression of FMOD and DCN was associated with downregulation of NF-κB and TGF-β1." (PMID 34283070, 2021).
breast carcinoma (continued). "In the tumor xenografts in mice induced with human breast cancer MDA-MB-231 cells, expression of FMOD and β-catenin was elevated, Aspirin treatment greatly reduced FMOD mRNA expression, β-catenin phosphorylation was increased, and p-ERK/ERK1/2 protein levels were reduced." (PMID 31824307, 2019). "To understand the role of FMOD gene expression in breast cancer metastasis in relation to Aspirin and the Wnt/β-catenin signaling pathway, we measured the mRNA and protein levels of FMOD, in the presence and absence of interference of the Wnt/β-catenin pathway, by qPCR and Western blot." (PMID 31824307, 2019). "As an ECM protein, FMOD could be expected to play important roles in cancer, but there have been few studies on its involvement in cancer development in general, and essentially none reported in breast cancer metastasis in particular." (PMID 31824307, 2019).
leukemia (4 papers, 2014 to 2021). A malignant (clonal) hematologic disorder, involving hematopoietic stem cells and characterized by the presence of primitive or atypical myeloid or lymphoid cells in the bone marrow and the blood. "FAZF overexpression has been shown to cause G1 arrest and apoptosis in B cell lines, in addition LRR5 (FMOD) is highly overexpressed in some types of leukemias." (PMID 25011449, 2014).
melanoma (4 papers, 2022 to 2025). A malignant, usually aggressive tumor composed of atypical, neoplastic melanocytes. "Loss of FMOD significantly delayed BrM in our model, suggesting that its dysregulation might be specifically associated with melanoma brain colonization and growth." (PMID 35737114, 2022). "FMOD has yet to be linked to metastasis-initiating competence, while its roles in melanoma are currently unknown." (PMID 35737114, 2022). "We next studied FMOD expression in human melanoma samples employing quantitative immunofluorescence and tissue microarrays." (PMID 35737114, 2022). "Since our models are derived from a BRAFV600E PTEN-null melanoma, we first evaluated changes in PI3K/Akt and MAPK signaling associated FMOD and/or SOX2 loss." (PMID 35737114, 2022). "Many of these downregulated proteomic cargoes in melanoma sEVs, including collagens (COL1A1, COL3A1, COL6A1–A3, and COL14A1), matrix-associated proteoglycans (DCN, LUM, FMOD, OGN, and PRELP), and structural regulators (TNXB and PCOLCE), are key components of ECM organization and tensile strength." (PMID 41271007, 2025). "In our previous study, we show that fibromodulin (FMOD), a secreted proteoglycan, modulates the activation of YAP and TAZ, two transcriptional co-factors scarcely studied in melanoma, which induces aggressive variant cells to form VM, and to develop brain metastases." (PMID 38635031, 2024). "This suggests that FMOD might promote melanoma brain-metastatic relapse by altering endothelial barrier functions to facilitate the extravasation of cancer cells into the brain parenchyma." (PMID 35737114, 2022). "Thus, our study identifies FMOD and SOX2 cooperation as a novel regulatory mechanism that might be linked functionally to melanoma metastatic competence." (PMID 35737114, 2022). "Dual gene silencing of FMOD and SOX2 ablated VM and subsequent melanoma brain metastases." (PMID 38635031, 2024). "We identified FMOD, an aberrantly produced and secreted ECM molecule and SOX2, a transcription factor involved in self-renewal, as likely players that might cooperate or regulate closely coordinated programs driving the outgrowth of melanoma brain metastasis." (PMID 35737114, 2022). "Our data suggest a possible role of SOX2 in tumors with FMOD dysregulation; concomitant SOX2 upregulation might contribute to its association with the early development of melanoma BrMs, but not with disease aggressiveness." (PMID 35737114, 2022). "This suggests that FMOD and SOX2 might regulate metastatic competence without altering the tumorigenic properties and highlights their functional specificity in melanoma BrM." (PMID 35737114, 2022).
atherosclerosis (3 papers, 2023 to 2025). A disease characterized by the build-up of fatty material and calcium deposition in the arterial wall resulting in partial or complete occlusion of the arterial lumen. "Recently, FMOD has been found to act as a risk factor for atherosclerosis." (PMID 37483637, 2023). "However, more research is needed to further confirm the role of FMOD in the regulation of inflammation during atherosclerosis development." (PMID 37483637, 2023). "Consequently, it is indicated that FMOD may influence atherosclerotic plaque development by regulating the function of macrophages and SMCs, which suggests that FMOD may be a potential target for atherosclerosis treatment." (PMID 37483637, 2023). "One of the most differentially expressed genes, fibromodulin (FMOD, increased 2.8-fold in CAD), has a known connection to atherosclerosis, cardiomyopathy and ferroptosis (iron-dependent programmed cell death)." (PMID 37303712, 2023).
colorectal cancer (3 papers, 2018 to 2023). A primary or metastatic malignant neoplasm that affects the colon or rectum. "In vitro, RP4 has better effect in suppressing human colorectal cancer cell proliferation with a lower IC50 value when compared with FMOD antibody." (PMID 36986805, 2023).
keloid (3 papers, 2007 to 2025). An irregularly shaped, elevated mark on the skin caused by deposits of excessive amounts of collagen during wound healing. "Mechanistically, fibromodulin accelerates and prolongs the formation of the interleukin 1β-interleukin 1 receptor type 1-interleukin 1 receptor accessory protein ternary complex to increase the apoptosis of myofibroblasts and keloid- and hypertrophic scar-derived cells." (PMID 40221432, 2025). "Undoubtedly, a more comprehensive comparison among dermal fibroblasts derived from normal skin, keloid, and HS tissues from donors of broadly diverse races, genders, and ages, as well as different tissue locations, will further aid our understanding of FMOD’s anti-scarring potency." (PMID 40221432, 2025). "However, FMOD was capable of promoting IL1β expression in keloid- and HS-derived fibroblasts." (PMID 40221432, 2025). "In situ cross-sections of keloid tissue and the monolayer cells derived from keloid tissue were positive for matrix assembly-related markers including DCN, FMOD, TGF-β1, and TGF-β3." (PMID 32085797, 2020). "Moreover, akin to KB-AA35 cells, both IL1β and FMOD induced apoptosis in these abdomen keloid-derived dermal fibroblasts but not the normal skin-derived fibroblasts." (PMID 40221432, 2025). "In addition, our current data offers compelling evidence to suggest that, albeit not activated yet, human keloid- and HS-derived fibroblasts, or at least a subpopulation of these cells, can replicate the targeted apoptosis of BJ- and NHDF-converted myofibroblasts in response to IL1β and FMOD." (PMID 40221432, 2025).
lung carcinoma (3 papers, 2019 to 2023). "FMOD plays a key role in angiogenesis in lung cancer, wound healing, optical and cutaneous diseases related to angiogenesis." (PMID 31198406, 2019). "FMOD mRNA has been detected different clinical malignancies, such as breast, prostate, and lung carcinomas." (PMID 31198406, 2019).
mantle cell lymphoma (3 papers, 2013 to 2021). Mantle cell lymphoma is a rare form of malignant non-Hodgkin lymphoma affecting B lymphocytes in the lymph nodes in a region called the ``mantle zone''. "We demonstrated that FMOD was expressed at the gene and protein levels in CLL and mantle cell lymphoma (MCL) cells." (PMID 24499526, 2013).
atrial fibrillation (2 papers, 2023 to 2025). A disorder characterized by an electrocardiographic finding of a supraventricular arrhythmia characterized by the replacement of consistent P waves by rapid oscillations or fibrillatory waves that vary in size, shape and timing and are accompanied by an irregular ventricular response. "Fibromodulin (FMOD) expression increased in spontaneously hypertensive‐atrial fibrillation rat." (PMID 37904680, 2023).
benign prostatic hyperplasia (2 papers, 2022 to 2023). A non-cancerous nodular enlargement of the prostate gland. "Furthermore, in a study based on Brazilian individuals, FMOD gene variants were suggested to be potential biomarkers for prostate cancer and benign prostatic hyperplasia." (PMID 37509645, 2023).
cardiac hypertrophy (2 papers, 2018 to 2021). "To further pursue the role of FMOD in cardiac hypertrophy, we assessed CM size histologically on midventricular sections of FMOD-KO and WT hearts post-AB." (PMID 30052659, 2018). "It's worth noting that there is no relevant report about the roles of COMP, FMOD, AEBP1 and SULF1 in HOCM or even myocardial hypertrophy, implying the need for further exploration." (PMID 34362365, 2021).
cardiomyopathies (2 papers, 2022 to 2023). "In addition, ferroptosis-related genes could provide us with a novel direction of exploration in HCM and DCM, respectively, and 3 hub genes (POSTN, IGFBP5, and FMOD) could be potential biomarkers or therapeutic targets in cardiomyopathies." (PMID 35282347, 2022).
colon carcinoma (2 papers, 2017 to 2022). "Here, we investigated the effects of fibromodulin on stroma ECM in a syngeneic murine colon carcinoma model." (PMID 28827814, 2017). "Indeed, fibromodulin (FMOD), which has been shown to be expressed in models of colon carcinoma, can activate the innate complement response by direct binding of the globular head of the C1q complement molecule." (PMID 35269922, 2022).
COVID-19 (2 papers, 2023 to 2024). A disease caused by infection with severe acute respiratory syndrome coronavirus 2. "The most significant DEP observed in the TGF-β pathway was the upregulation of FMOD in the COVID-19 and PQ comparison groups, with a more pronounced difference observed in the PQ group." (PMID 39301288, 2024).
lung fibrosis (2 papers, 2023 to 2025). "Previous studies have evidenced that FMOD expression was upregulated during lung fibrosis and wound healing processes in the skin." (PMID 37904680, 2023).
systemic sclerosis (2 papers, 2019 to 2025). A chronic disorder, possibly autoimmune, marked by excessive production of collagen which results in hardening and thickening of body tissues. "Moreover, FMOD-induced myofibroblast apoptosis could also be beneficial for other pathologies associated with myofibroblast persistence, including autoimmune rheumatic diseases, such as systemic sclerosis, rheumatoid arthritis, as well as liver, kidney, and muscle fibrosis." (PMID 40221432, 2025).
aging (1 paper, 2024). A developmental process that is a deterioration and loss of function over time. "In this study, we identified thrombospondin-1 (THBS1) and fibromodulin (FMOD) as positive and negative regulators, respectively, of the TGF-β1-SMAD4 axis in human skin aging, based on in vitro and in vivo omics analyses and mathematical modeling." (PMID 38706856, 2024).
anaplastic thyroid carcinoma (1 paper, 2022). "This is consistent with a previous study in human anaplastic thyroid carcinoma, which found that FMOD was not implicated in vessel formation in vivo." (PMID 35737114, 2022).